CLU (clusterin)
Diseases named in the same sentence as CLU in open-access papers (continued):
Sharing a sentence is not in itself a finding about the gene and the disease.
pancreatic cancer (continued). "CLU knockout represses proliferation in pancreatic cancer by inducing cellular senescence." (PMID 37628784, 2023). "APOJ, or Clusterin (CLU), is a well-studied apolipoprotein in the context of pancreatic cancer." (PMID 38067270, 2023). "A study highlighted that CLU expression in pancreatic cancer is regulated by HSF1, a stress-induced master regulator that is known to play a key role in converting fibroblasts into cancer-associated fibroblasts (CAFs) in pancreatic cancer and other cancers." (PMID 38067270, 2023). "In addition, the second most upregulated gene in the biliary-like group was the anti-apoptotic gene clusterin (10 fold increase), which has been correlated with chemoresistance in pancreatic cancer." (PMID 23776447, 2013). "Clusterin inhibition could augment the chemosensitivity of human pancreatic cancer cells by inhibition of clusterin-dependent pERK1/2 activation." (PMID 22967941, 2012). "In a recent study, the possibility that clusterin expression may confer gemcitabine resistance in pancreatic cancer was suggested." (PMID 22799602, 2012). "However, the role played by clusterin in pancreatic cancer cells is still unclear, and its clinical significance has yet to be determined." (PMID 22799602, 2012). "Taken together, clusterin confers gmcitabine resistance in pancreatic cancer cells." (PMID 22967941, 2012). "Furthermore, clusterin is also known to be overexpressed in various cancer tissues, including pancreatic cancer." (PMID 22799602, 2012). "However, few reports have addressed the relationship between the manifestation of clusterin and clinicopathologic parameters in pancreas cancer patients." (PMID 22799602, 2012). "Our finding that clusterin expression was significantly higher in pancreatic cancer than in normal pancreatic tissues suggests that clusterin may confer gmcitabine resistance in pancreatic cancer cells." (PMID 21609464, 2011). "In conclusion, we have shown here that clusterin expression was significantly higher in pancreatic cancer tumor samples than in normal pancreas tissues and that clusterin expression was significantly correlated with gmcitabine resistance in pancreatic cancer cell lines." (PMID 21609464, 2011). "The correlation between clusterin expression level and gmcitabine IC50 in pancreatic cancer cell lines was evaluated." (PMID 21609464, 2011). "Therefore, in the present study, we evaluated the effect of decrease in clusterin expression in the human pancreatic cancer BxPC-3 cells using AS ODN, and study whether downregulation of clusterin increase their sensitivity cytotoxic chemotherapy both in vitro and in vivo." (PMID 21609464, 2011). "A recent study demonstrated that CLU suppression induces senescence and reduces proliferation in pancreatic cancer cell lines; however, apoptosis markers showed no significant changes in CLU-silenced cells, leaving the underlying mechanism unclear." (PMID 40573993, 2025). "Interestingly, inhibition of CLU and SCD has been previously shown to suppress proliferation of pancreatic cancer cells and pancreatic tumor growth." (PMID 37978383, 2023). "Using three CAF markers—Clusterin (CLU), αSMA, and MHC class II—we identify three mutually exclusive CAF subtypes in primary pancreatic tumor resection specimens, and show that the ratio between these CAF subtypes is altered in BRCA-mut tumors compared to BRCA-WT tumors." (PMID 36316305, 2022). "Of the 50 pancreatic cancer tissues, 26 (52%)exhibited clusterin overexpression in cancer cells, 4(8%) exhibited clusterin weak expression in cancer cells, and no clusterin staining was shown in 20 pancreatic cancertissues." (PMID 21609464, 2011). "In the present study, we showed a significant correlation between clusterin expression and gmcitabine IC50 in the pancreatic cancer cell lines, we tested the hypothesis that clusterin expression may confer gmcitabine resistance in pancreatic cancer cells." (PMID 21609464, 2011).
pancreatic cancer (continued). "Clusterin expression was challenged using the drug OGX-011, an antisense oligonucleotide that showed a potentiating effect on various FDA-approved anticancer chemotherapeutics during clinical trials; however, no trial in pancreatic cancer has been programmed yet." (PMID 37835519, 2023).
Parkinson disease (20 papers, 2011 to 2025). A progressive degenerative disorder of the central nervous system characterized by loss of dopamine producing neurons in the substantia nigra and the presence of Lewy bodies in the substantia nigra and locus coeruleus. "CLU has also been documented to play an important role in Parkinson's disease, being significantly related to a higher risk of PD development, especially in males; a potential role of clusterin in preventing α-synuclein aggregation has also been suggested." (PMID 36071866, 2022). "Both, S100B and CLU, are associated with many neurological disorders such as Alzheimer’s disease and Parkinson’s disease in humans that involve hypoxia and oxidative stress." (PMID 36243678, 2022). "The expression of CLU rs9331896 allele was shown to be associated with a significantly higher risk of Parkinson's disease development in the Chinese Han population, especially in males." (PMID 36071866, 2022). "The CLU-rs9331896-TT genotype is even a risk factor for Parkinson's disease." (PMID 35788904, 2023). "Similar to S100B, in proteinopathies like Alzheimer’s and Parkinson’s disease, CLU has been found to associate with protein aggregates and might be involved in their clearance." (PMID 36243678, 2022). "Overall, our observations indicate that clusterin can limit the uptake of extracellular α‐synuclein aggregates by astrocytes and, hence, contribute to the spreading of Parkinson pathology." (PMID 33045109, 2021). "We confirmed that exosomal clusterin is elevated in subjects with 4‐repeat tauopathy, and when combined with α‐synuclein, it improved the performance of the assay in differentiating Parkinson's disease from 4‐repeat tauopathies to AUC, 0.98 versus 0.99." (PMID 33826157, 2021). "Increased α-synuclein egress in serum neuronal exosomes precedes the diagnosis of Parkinson’s disease, persists with disease progression and in combination with clusterin predicts and differentiates Parkinson’s disease from atypical parkinsonism." (PMID 32273329, 2020). "Combined neuron-derived exosomal α-synuclein and clusterin measurement predicted Parkinson’s disease from other proteinopathies with AUC=0.98 and from multiple system atrophy with AUC=0.94." (PMID 32273329, 2020). "CLU also plays a role in other neurodegenerative diseases such as Parkinson’s disease and ALS." (PMID 39627493, 2025). "For example, we have recently demonstrated that the composite measurement of α-synuclein and clusterin in serum L1CAM-positive EVs was highly accurate (AUC = 0.98) in differentiating Parkinson’s disease from atypical parkinsonism using 735 samples from four independent cohorts." (PMID 34855021, 2021). "Direct explorations of potential roles of clusterin in Parkinson pathogenesis are rare." (PMID 21912625, 2011). "Studies suggest that CLU may play a neuroprotective role by preventing the aggregation of proteins such as amyloid-beta and alpha-synuclein, which play a key role in Alzheimer's and Parkinson's disease, respectively." (PMID 39253532, 2024). "We assumed that clusterin might play a protective role (as a compensatory mechanism) in psoriasis, metabolic syndrome, and other inflammatory (e.g., rheumatoid arthritis and atopic dermatitis) and neurodegenerative (e.g., Alzheimer’s and Parkinson’s) diseases." (PMID 32764517, 2020). "Clusterin levels are elevated in synovial fluid of rheumatoid arthritis and osteoarthritis patients and in the cerebrospinal fluid of patients with AD, Parkinson disease, and multiple sclerosis (85, –, 87), as well as in the urine of patients with kidney injury or bladder cancer." (PMID 24366862, 2014). "In addition, the authors did not observe any correlation between CSF clusterin and patients’ gender or age or the disease duration, stage (determined using Hoehn and Yahr classification, or severity expressed using the motor subscale of the Unified Parkinson’s Disease Rating Scale (UPDRS-III)." (PMID 35326174, 2022).
colorectal cancer (19 papers, 2009 to 2025). A primary or metastatic malignant neoplasm that affects the colon or rectum. "Using multivariate logistic models a significant positive association emerged for clusterin, with an 80% increase in the colorectal cancer risk with protein’s unit increase, but only in men." (PMID 25884309, 2015). "The high circulating clusterin in pre-diagnostic samples suggests this biomarker can improve the identification of people at risk of colorectal cancer and might help in designing preventive interventions." (PMID 25884309, 2015). "We note that sequencing studies report that clusterin is typically lower in expression in colorectal cancer than normal tissue, and the observation of longer OS of patients with the CRLM-CA phenotype suggests clusterin can also provide a cytoprotective role." (PMID 40617497, 2025). "This upregulation of MEG3 exerts tumor suppressor effects in colorectal cancer by regulating the activity of Clusterin." (PMID 39830506, 2024). "The aim of this paper is to review the current genetic knowledge on the role of CLU in tumorigenesis and cancer progression in general, and discuss its possible use as a therapeutic target in colorectal cancer." (PMID 37834086, 2023). "In recent years, the relationship between clusterin and colorectal cancer (CRC) has been investigated from a genetic perspective." (PMID 37834086, 2023). "In colorectal cancer, L1CAM caused upregulation of clusterin expression in cancer cells as a result of the transactivating effect of STAT1 on clusterin." (PMID 35003395, 2021). "Moreover, some authors reported that IL-6 modulates CLU expression in colorectal cancer, which can also be applied to the pathogenesis of other inflammatory diseases, including RA." (PMID 39684771, 2024). "They found that elevated levels of clusterin mRNA in colorectal cancer tumors could predict an adverse prognosis for patients with Grade II and/or TNM stage III cancer." (PMID 37834086, 2023). "A growing number of studies suggest that CLU can act as a target for colorectal cancer therapy, and high expression of CLU may indicate chemoresistance." (PMID 36267311, 2022). "Based on the results obtained, the authors suggested that the high levels of CLU mRNA may be usable as an adverse prognostic biomarker for disease-free survival and overall survival in colorectal cancer." (PMID 36071866, 2022). "Preliminary evidence also suggests that measurement of clusterin in serum and plasma may be useful for the early detection of colorectal cancer and for monitoring pVHL-defective renal carcinomas." (PMID 19348683, 2009). "We also observed changes in clusterin protein levels in CRC cell lines (HCT116) under various culture conditions (TCCM/ORG/M-ORG), as well as in colorectal-cancer-patient-derived organoids (CRC-166T)." (PMID 38067236, 2023). "Notably, several significantly altered proteins, including APOA4, CLU, and SAA4, have previously been reported as potential biomarkers for colorectal cancer." (PMID 41367384, 2025). "We selected three candidate colorectal cancer biomarkers (B2M, TIMP-1, and CLU)." (PMID 36792801, 2023).
Brain atrophy (18 papers, 2010 to 2025). Partial or complete wasting (loss) of brain tissue that was once present. "Our results echo previous research findings, showcasing that elevated levels of clusterin are associated with a slower rate of brain atrophy, notably in critical regions implicated in cognitive functions such as the hippocampus and the broader brain structure." (PMID 37941999, 2023). "In a later work, they studied the relationship between plasma clusterin (apolipoprotein J) concentration and longitudinal brain atrophy, finding significant associations." (PMID 30830917, 2019). "In patients with MCI, higher baseline levels of plasma clusterin have been associated with lower rates of brain atrophy." (PMID 29169407, 2017). "In conclusion, the plasma ratio of Aβ1-42/Aβ1-40 and clusterin level may be associated with different patterns of regional brain atrophy, which in turn may account for the clinical symptoms in patients with AD." (PMID 28698646, 2017). "Adding weight to our hypothesis that changes in plasma clusterin were an early event, increased levels of plasma clusterin in association with slower rates of brain atrophy in MCI were demonstrated." (PMID 26635716, 2015). "Moreover, higher clusterin concentrations in plasma have been associated with slower rates of brain atrophy in mild cognitive (MCI) patients." (PMID 26179372, 2015). "Their research demonstrated that elevated clusterin levels correlated with a slower pace of brain atrophy." (PMID 37941999, 2023). "We examined associations among cognition, NPI score, plasma β-amyloid (Aβ) and clusterin levels, and regional brain atrophy in patients with AD by regression analysis." (PMID 28698646, 2017). "CLU upregulation may play a protective function, but a correlation between increased CLU and brain atrophy and rapid clinical progression in AD patients has also been observed." (PMID 39448576, 2024). "Additional studies are needed to examine the pattern of association between clusterin and brain volumes, and to assess the extent that lower and higher clusterin may be related to patterns of AD-related brain atrophy." (PMID 29324756, 2018). "Moreover, clusterin is associated with the early stages of AD pathology, and plasma clusterin is related to longitudinal brain atrophy in MCI patients." (PMID 27516739, 2016). "In addition, plasma clusterin is related to brain atrophy, baseline disease severity, and rapid clinical progression in AD." (PMID 27516739, 2016). "Interestingly, we found that different sets of proteins were associated with brain atrophy in MCI compared to AD, indicating that these markers are disease-phase specific, and the strongest associations with brain atrophy were observed for clusterin in the MCI group and ApoE in the AD group." (PMID 26635716, 2015). "For the primary analysis, we used an additive model to assess whether the following late onset AD-associated variants influence brain atrophy and cognitive dysfunction in MS patients: PICALM (rs3851179), CR1 (rs6656401), CLU (rs11136000), PCK1 (rs8192708), and ZNF224 (rs3746319)." (PMID 21152065, 2010).
cognitive decline (17 papers, 2012 to 2025). "Both signatures also share two common molecules, protein 14-3-3 zeta/delta and clusterin, suggesting these belong to common biological pathways both associated with AD and relevant for cognitive decline." (PMID 33794997, 2021). "Single nucleotide polymorphisms in clusterin have also been linked to early cognitive decline in PD." (PMID 33192447, 2020). "A previous study reported that higher concentrations of plasma clusterin were significantly associated with an accelerated cognitive decline in patients with AD after 1 year of follow-up." (PMID 29169407, 2017). "While very recently increased plasma clusterin levels have been associated with increased risk of conversion to AD and rate of cognitive decline in an independent study." (PMID 26635716, 2015). "Our data suggest that Clusterin may play a key role in the impaired myelin repair observed in AD and could serve as a promising therapeutic target for addressing AD-associated cognitive decline." (PMID 38853911, 2024). "For example, clusterin, a protein linked to hippocampal atrophy and cognitive decline, has shown promise, though its elevation may arise from various unrelated pathological processes." (PMID 39596023, 2024). "What’s more, our data linking clusterin and myelin dysregulation is supported by MRI data demonstrating that the clusterin risk allele is associated with a decrease in white matter integrity in healthy young adults, prior to onset of any cognitive decline." (PMID 38853911, 2024). "In the present study CLU genotypes and haplotypes were associated with baseline cognition and the rate of cognitive decline in two cohorts, the Danish 1905 birth cohort (93 years of age in 1998) and the Longitudinal Study of Aging Danish twins (LSADT) (73–83 year old twins in 1997)." (PMID 24244428, 2013). "Further, adding to a reference model for the prediction of cognitive decline, four selected molecules, protein 14-3-3 zeta/delta, clusterin, cholesteryl ester 27:1 16:0, and monocyte chemoattractant protein-1, improved its AUC (p value = 0.0047)." (PMID 33794997, 2021). "It remains to be determined if elevations in clusterin are a consequence of a distinct disease progression that results in reduced cognitive decline, or instead represent a homeostatic means to provide neurological protection." (PMID 33192447, 2020). "Literature shows that ApoE4 and plasma clusterin are biomarkers for an accelerated cognitive decline in AD." (PMID 29169407, 2017). "As an option, interventions that stimulate clusterin expression probably result in a beneficial effect for subjects with cognitive decline." (PMID 27516739, 2016). "Additionally, glial clusterin expression was higher in cases of ALS with cognitive decline than in controls or mismatch cases." (PMID 33192447, 2020). "The plasma level of clusterin could be a prognostic marker for patients with AD, but the specific relationship between the clusterin level and cognitive decline remains to be determined." (PMID 29169407, 2017). "Further investigations should be conducted to determine the role of clusterin in cognitive decline." (PMID 27516739, 2016). "Besides, our study found that neuroimaging markers might mediate the associations between CSF complement proteins (C1q, C2, C5, CFB and clusterin) and cognitive decline." (PMID 38238858, 2024). "Finally, combinations of four molecules improved prediction of both AD (protein 14-3-3 zeta/delta, clusterin, interleukin-15, and transgelin-2) and cognitive decline (protein 14-3-3 zeta/delta, clusterin, cholesteryl ester 27:1 16:0 and monocyte chemoattractant protein-1)." (PMID 33794997, 2021). "Plasma clusterin could serve as a biomarker for the severity of cognitive decline." (PMID 29169407, 2017). "This evidence could possibly also indicate that the CLU gene variant is associated with later onset of cognitive decline rather than having a protective role for cognitive decline as such." (PMID 24244428, 2013).